HELQ (helicase, POLQ like)
Description:
Single-stranded 3'-5' DNA helicase that plays a key role in homology-driven double-strand break (DSB) repair. Involved in different DSB repair mechanisms that are guided by annealing of extensive stretches of complementary bases at break ends, such as microhomology-mediated end-joining (MMEJ), single-strand annealing (SSA) or synthesis-dependent strand annealing (SDSA). Possesses both DNA unwinding and annealing activities. Forms a complex with RAD51, stimulating HELQ DNA helicase activity and ability to unwing DNA. Efficiently unwinds substrates containing 3' overhangs or a D-loop. In contrast, interaction with the replication protein A (RPA/RP-A) complex inhibits DNA unwinding by HELQ but strongly stimulates DNA strand annealing. Triggers displacement of RPA from single-stranded DNA to facilitate annealing of complementary sequences.
Synonyms: HEL308
Tractability: PROTAC: ubiquitination databases record sites on it.
Gene: Protein-coding gene on chromosome 4 (83,407,343 to 83,455,855, reverse strand). Ensembl gene ENSG00000163312.
Subcellular location: Nucleus; Chromosome
Subcellular location (Human Protein Atlas): Nuclear speckles; Nucleoplasm
Gene Ontology:
Molecular function: 3'-5' DNA helicase activity; ATP hydrolysis activity; protein binding; single-stranded 3'-5' DNA helicase activity; single-stranded DNA helicase activity; ATP binding; nucleic acid binding
Biological process: DNA double-strand break processing involved in repair via single-strand annealing; double-strand break repair via alternative nonhomologous end joining; double-strand break repair via homologous recombination; double-strand break repair via synthesis-dependent strand annealing; positive regulation of double-strand break repair via homologous recombination
Cellular component: chromosome; nucleus; site of DNA damage
Genetic constraint (gnomAD): Loss-of-function variants: 27 observed, 50.19 expected, observed/expected ratio (o/e) 0.54, 90% interval 0.4 to 0.74. The upper end of that interval is the gene's LOEUF score, 0.74, which puts it in group 3 of 6, group 1 being the genes least tolerant of losing a copy. Missense variants: 732 observed, 804.49 expected, observed/expected ratio (o/e) 0.91, 90% interval 0.86 to 0.97. Synonymous variants: 268 observed, 294.16 expected, observed/expected ratio (o/e) 0.91, 90% interval 0.82 to 1.01.
Homologues: Orthologues: chimpanzee HELQ (99% identical), macaque HELQ (97% identical), rabbit HELQ (83% identical), pig HELQ (82% identical), guinea pig HELQ (75% identical), rat Helq (75% identical), mouse Helq (75% identical), tropical clawed frog helq (58% identical), zebrafish helq (52% identical), dog HELQ (46% identical), Drosophila melanogaster mus301 (35% identical), Caenorhabditis elegans helq-1 (30% identical). Paralogues in human: POLQ (27% identical), HFM1 (17% identical), SNRNP200 (17% identical), DDX60 (17% identical), DDX60L (16% identical), ASCC3 (15% identical), SKIC2 (15% identical), MTREX (13% identical).
Diseases named in the same sentence as HELQ in open-access papers:
HELQ is named in the same sentence as 24 diseases in open-access papers, as found by Europe PMC text mining. Sharing a sentence is not in itself a finding about the gene and the disease. The quoted sentences say what the papers report.
ovarian carcinoma (6 papers, 2013 to 2025). A malignant neoplasm originating from the surface ovarian epithelium. "Current data from The Cancer Genome Atlas (TCGA) shows that the frequency of heterozygous loss of HELQ in ovarian cancer is comparable to RAD51C and RAD51D." (PMID 24005565, 2013). "The association with RAD51 paralogs and the frequent copy number loss of HELQ in ovarian cancers suggests HELQ as a candidate ovarian cancer predisposition gene." (PMID 24005565, 2013). "Further, the association with RAD51 paralogs suggests HELQ as a candidate ovarian cancer gene." (PMID 24005565, 2013). "Conversely, HELQ knockdown results in the opposite effects, positioning HELQ as a potential novel biomarker for chemoresistance in epithelial ovarian cancer (EOC) and a prognostic predictor." (PMID 39201320, 2024). "Recent studies have illuminated HELQ’s pivotal role not only in ovarian cancer but also across a spectrum of other cancer types." (PMID 39201320, 2024). "Currently, numerous studies have shown that HELQ primarily plays a crucial role in inhibiting the occurrence and progression of ovarian cancer, and it also exhibits partial effects in some other types of cancer." (PMID 39201320, 2024). "Overall, HELQ’s role appears pivotal in inhibiting the occurrence and progression of ovarian cancer." (PMID 39201320, 2024). "Understanding these mechanisms provides a foundation for exploring HELQ as a therapeutic target not only in ovarian cancer but also in other malignancies where DSB repair is compromised." (PMID 39201320, 2024). "Our study has confirmed that ovarian cancer patients with the high expression of HELQ or XAB2 had decreased PFS and OS, respectively." (PMID 35392433, 2022). "The connection described here between HELQ and the RAD51 paralogs suggests that HELQ is a candidate gene for loss or mutation in sporadic or inherited ovarian cancer." (PMID 24005565, 2013). "For example, screening of 185 Finnish breast or ovarian cancer families for germline variation in the HELQ gene showed no likely causative variants." (PMID 38540391, 2024). "HELQ plays a crucial role in inhibiting the onset and progression of ovarian cancer." (PMID 39201320, 2024). "In addition, over-expression of HelQ promotes resistance to treatments for ovarian cancers that are based on use of DNA crosslinkers, implicating HelQ levels in cells as potential factor to be overcome in hard-to-treat cancers." (PMID 34316696, 2021). "NER-related genes including HELQ and XAB2 expressions were determined via immunocytochemistry in ascites cell samples from 92 ovarian cancer patients prior to primary cytoreduction surgery." (PMID 35392433, 2022). "However, the mechanism of HELQ and XAB2 leading to platinum resistance in ovarian cancer needs further exploration." (PMID 35392433, 2022).
breast carcinoma (3 papers, 2016 to 2024). "A high expression of HELQ in patients with high–grade serous ovarian cancer and breast cancer is associated with a poor prognosis." (PMID 39201320, 2024). "Expression QTL analysis in breast cancer tissue showed rs11099601 to be associated with HELQ (P = 8.28x10-14), MRPS18C (P = 1.94x10-27) and FAM175A (P = 3.83x10-3), explaining about 20%, 14% and 1%, respectively of the variance inexpression of these genes in breast carcinomas." (PMID 27792995, 2016). "The strongest associations for rs11099601 and expression were observed in breast carcinomas for MRPS18C and HELQ and explain approximately 14% and 20% of their expression variance, respectively." (PMID 27792995, 2016). "Indeed, analysis of TCGA breast cancer RNAseq data showed that HELQ, FAM175A and HPSE were found to be differentially expressed between normal breast and tumor tissue and further analysis showed that HELQ and FAM175A expression levels are significantly decreased in basal-like tumors." (PMID 27792995, 2016). "This study did not provide evidence for a role of HELQ in breast cancer susceptibility in the Finnish population, but analyses in other populations and larger datasets are needed to further assess its role in breast cancer predisposition, especially with regard to the involvement of rare variants." (PMID 27792995, 2016).
Infertility (3 papers, 2022 to 2025). "HELQ is another gene involved, essential for the repair of double-stranded DNA breaks, and its alteration is also known to cause infertility in mice." (PMID 41488147, 2025). "A recent study investigating candidate variants in infertile men with Sertoli cell‐only syndrome shed light on the potential correlation between HELQ mutations and infertility." (PMID 38720471, 2024). "A recent study using a set of 183 infertile men diagnosed with Sertoli cell‐only syndrome discovered the mutation of HELQ in six male infertile patients, indicating the correlation between HELQ mutation and male infertility." (PMID 38720471, 2024). "HELQ is a superfamily 2 helicase with 3′ to 5′ polarity, and its disruption in mice confers germ cells loss, infertility and increased predisposition to ovarian and pituitary tumours." (PMID 34937945, 2022). "A recent study identified two HELQ missense mutations in some cases of infertile men." (PMID 38720471, 2024).
chronic lymphocytic leukemia (2 papers, 2021 to 2024). "Additionally, HELQ and EGR3 expression levels were associated with the mutation status of the heavy chain variable region (IgHV) in patients with chronic lymphocytic leukemia (CLL), indicating that HELQ/EGR3 is a potential prognostic marker linked to targeted cell signaling pathways." (PMID 39201320, 2024).
Fanconi anaemia (2 papers, 2013 to 2021). "Proteins of the Fanconi anemia complementation group are key components for overcoming ICLs and other replication blocking lesions in human cells, but HelQ seems to act independently from them." (PMID 34316696, 2021). "Though previous studies have suggested the possibility that HELQ is involved in the Fanconi anemia (FA) pathway, a dominant mechanism for inter-strand crosslink repair in vertebrates, this connection remains elusive." (PMID 24005041, 2013).
Ascites (1 paper, 2022). Accumulation of fluid in the peritoneal cavity (between the layers of the peritoneum that lines the abdomen). "The expression levels of HELQ (RR 5.7, 95% CI 1.7-19.2) and XAB2 (RR 3.2, 95% CI 0.9-10.8) in ascites tumor cells were positively correlated to the risk of platinum resistance." (PMID 35392433, 2022). "In summary, our findings demonstrated that immunocytochemistry for HELQ and XAB2 expressions in ascites tumor cells are applicable in prediction of the primary response to chemotherapy and prognosis." (PMID 35392433, 2022).
gastric adenocarcinoma (1 paper, 2023). "One of these patients had gastric adenocarcinoma, and was found to have somatic alterations in RIF1 and HELQ, both of which are genes known to be involved in the HR pathway." (PMID 36964191, 2023).
hypogonadism (1 paper, 2013). A disorder characterized by decreased function of the gonads. "As previous studies suggested an intriguing connection of HELQ to the FA pathway, we generated Helqgt/gt mice along with WT control mice to examine hypogonadism, one of the most consistent phenotypes seen in the FA mouse models." (PMID 24005041, 2013).
lymphoid neoplasm (1 paper, 2021). A neoplasm composed of a lymphocytic cell population which is usually malignant (clonal) by molecular genetic and/or immunophenotypic analysis. "The expression was significantly differential across various types of lymphoid neoplasms for HELQ/EGR3/ZNF667." (PMID 33485349, 2021). "Moreover, HELQ, EGR3 and ZNF667 were expressed differentially among diverse types of lymphoid neoplasm." (PMID 33485349, 2021).
male infertility (1 paper, 2024). The inability of the male to effect fertilization of an ovum after a specified period of unprotected intercourse. "Helicase POLQ‐like (HELQ) is an essential DNA helicase for maintaining genomic stability, and its mutations have been associated with male infertility." (PMID 38720471, 2024).
Primary amenorrhea (1 paper, 2024). "In conclusion, we have identified a homozygous missense variant in HELQ (p.Gln199Pro) in a woman with POI presenting as primary amenorrhea." (PMID 38540391, 2024).
Richter syndrome (1 paper, 2021). Transformation of chronic lymphocytic leukemia into aggressive non-Hodgkin's lymphoma, usually diffuse large B-cell lymphoma (immunoblastic or centroblastic variant). "HELQ expression was found to be related with response of immunochemotherapy treatment significantly (p = 0.0413), while HELQ and ZNF667 were expressed differently between stable CLL and Richter syndrome patients (p < 0.0001 and p = 0.0278, respectively)." (PMID 33485349, 2021).
cancer (10 papers, 2013 to 2024). A tumor composed of atypical neoplastic, often pleomorphic cells that invade other tissues. "Several other mutations and polymorphisms in HELQ have been identified in various sequenced cancers." (PMID 24005565, 2013). "Although HELQ-deficient human and mouse cells are more sensitive to DNA interstrand crosslinks (ICLs)-inducing agents, suggesting a role for HELQ in the processing of ICLs and tumour suppression, the role of HELQ in cancer development requires further elucidation." (PMID 38540391, 2024). "By targeting HELQ and modulating its activity, new therapeutic approaches could be developed to enhance the efficacy of existing treatments and potentially prevent the onset of cancer in high–risk individuals." (PMID 39201320, 2024). "We currently lack a comprehensive understanding of the role of HELQ in cancer development." (PMID 38540391, 2024). "Our work thus implicates HELQ activity for all DSB repair modes guided by complementary base pairs and provides mechanistic insight into mutational signatures common in HR-defective cancers." (PMID 34880204, 2021). "Involvement of HelQ in overcoming DNA damage that blocks replication makes it a potential stand-alone helicase target for improving the efficacy of cancer treatments that rely on replication blocking agents to kill cancer cells." (PMID 34316696, 2021). "The capacity for homologous recombination must be sustained in order to maintain human ovarian function with age56, indicating that alterations in HELQ may be relevant to both cancer and aging." (PMID 24005565, 2013). "Furthermore, as HELQ remains functional in FA mutant cells, it could potentially be exploited to provide a therapeutic benefit against cancers with FA pathway disruption." (PMID 24005041, 2013). "Conversely, RAD52–driven MiDAS in cancer cells may be adapted to prevent chromosome mis-segregation, potentially impacting CFS expression, unlike the synergistic effect of HELQ and FANCD2 in promoting ICL repair." (PMID 39201320, 2024).
tumor (9 papers, 2012 to 2024). "HELQ, an enzyme involved in DNA repair, plays a crucial role in repairing DNA cross-links and has been linked to germ cell maintenance, fertility, and tumour suppression in mice." (PMID 38540391, 2024). "This inability to resolve stalled replication forks is linked to attrition of germ cells and tumor susceptibility of HELQ-deficient mice." (PMID 32369918, 2020). "HELQ is a member of the DNA repair process related to tumor predisposition." (PMID 33095795, 2020). "The combined deletion of HELQ and CtIP results in heightened sensitivity to replication stress and exhibits synergistic lethal effects on tumor cells." (PMID 39201320, 2024). "It was later confirmed that HELQ does have a role in Drosophila, Caenorhabditis elegans, or mammalian tumor cells, demonstrating its significance in participating in ICL." (PMID 39201320, 2024). "Then, we investigated the relative expression of HELQ and XAB2 in ascites tumor cells utilizing ROC curves, to evaluate the performance of HELQ and XAB2 as predictors." (PMID 35392433, 2022). "Subsequent analyses of HELQ and XAB2 expressions in ascites tumor cells and clinical data showed statistically significant increased distribution of platinum resistance in patients with high-expression of HELQ (P < 0.001) and XAB2 (P = 0.006)." (PMID 35392433, 2022). "In the training cohort of 60 patients, better survival was strongly associated with low expression of HELQ and XAB2 in ascites tumor cells." (PMID 35392433, 2022). "To validate the reliability of HELQ and XAB2 results in ascites tumor cells, we also determined the expression of HELQ and XAB2 in paired primary tumor tissues." (PMID 35392433, 2022). "The importance of HELQ for normal DNA repair is demonstrated by the high tumor incidence seen in HELQ–/– mice." (PMID 32369918, 2020). "HELQ is a DNA helicase involved in replication-coupled DNA repair that has previous evidence of a tumour suppressor function." (PMID 29089486, 2017). "Finally, exploring the corresponding DSB repair function of HELQ based on its biochemical activity and molecular structure characteristics is of great significance for predicting certain tumors or developing anti–tumor–targeted drugs." (PMID 39201320, 2024). "Therefore, investigating the functional abnormalities of HELQ that contribute to this poor prognosis will be beneficial for the development of anti-tumor–targeted drugs." (PMID 39201320, 2024). "Adjacent tumour suppressor pairs (e.g., CDKN2A/CDKN2B, BIRC2/BIRC3, HELQ/FAM175A...) may be especially rewarding targets for homozygous deletion in some cases, as two mutation events can abolish all tumour suppressor activity." (PMID 29089486, 2017). "To confirm the correlation between HELQ and XAB2 expressions and platinum-based chemotherapy response in HGSC, we noticed that high expression of HELQ and XAB2 in ascites tumor cells were strongly correlated with platinum resistance." (PMID 35392433, 2022). "Consistent with ascites samples, a trend toward platinum resistance enrichment was observed in cases with high expression of HELQ and XAB2 in paired tumor tissues, which supported HELQ and XAB2 as predictors of platinum resistance." (PMID 35392433, 2022). "A recent study revealed that HELQ (Helicase, POLQ-like) plays a critical role in replication-coupled DNA repair, germ cell maintenance and tumor suppression in mammals." (PMID 34107880, 2021). "We observed platinum resistance enrichment in the high expression of HELQ (9/15 vs. 3/45, P < 0.001) and XAB2 (7/15 vs. 5/45, P = 0.006), suggesting that HELQ and XAB2 expressions in ascites tumor cells could be predictors of platinum resistance in HGSC." (PMID 35392433, 2022). "Our current finding showed that HELQ and XAB2 expressions in the ascites tumor cells correlated with HGSC patient's response to platinum-based chemotherapy and clinical outcomes indicate the potentiality of HELQ and XAB2 as independent biomarkers to predict HGSC patients' response to platinum drugs." (PMID 35392433, 2022).
tumor (continued). "In this study, the high expression of HELQ and XAB2 in ascites tumor cells may lead to an increase of the ability of DNA damage repair, such as the HR or NER pathway, and a decrease in apoptosis, which led to tumor cell tolerance to platinum drugs." (PMID 35392433, 2022).
HELQ also shares sentences with these, for which no sentence is quoted: osteosarcoma (2 papers); Serous Ovarian Cancer (2); anemia (1); breast tumors (1); ependymoma (1); female infertility (1); head and neck cancer (1); lymphoma (1); oesophageal cancers (1); oral cavity cancer (1).